IL10 (interleukin 10)
Diseases named in the same sentence as IL10 in open-access papers (continued):
Sharing a sentence is not in itself a finding about the gene and the disease.
tumor (continued). "Tumor cells promote the suppression of host anti-tumor type 1 T cell responses by various mechanisms, including the upregulation of surface inhibitory molecules such as programmed death ligand (PD-L)-1, and the production of immunosuppressive cytokines such as interleukin-10 (IL-10)." (PMID 34832887, 2021). "Therefore, combining IL-10 and hTERT could generate more tumor specific CD8+ T cells in more organs than single treatment." (PMID 33717103, 2021). "Importantly, the co-culture with the CMAS KO tumour cells showed reduced IL-10 production." (PMID 33627655, 2021). "Furthermore, exercise could effectively reduce the tumor volume, lower levels of proinflammatory cytokines TNFα, increase the anti-inflammatory cytokine IL-10 by regulating miR-21a-5p expression." (PMID 34099844, 2021). "However, the exact effects on tumor progression, whether tumor-promoting or -suppressive, should be further investigated owing to the dual role of IL-10 in cancer development." (PMID 33578830, 2021). "Anticancer effects of these compounds and their combination with cisplatin were assessed in this tumor mouse model with bioluminescent signaling and histopathology, and a cytokine assay was used to examine expression of inflammatory cytokines IL-1β, IL-6, IL-10, and TNF-α from plasma samples." (PMID 32174830, 2020). "Also for IL‐10−/− mice a similar total tumor incidence was found." (PMID 32350866, 2020). "Accumulating evidences indicated that inhibition of the MAPK pathway in melanoma cells may result in the block of the production of tumor-derived immunosuppressive or pro-angiogenetic factors including IL-6, IL-10 and VEGF that are essential for cancer immune evasion and growth." (PMID 32218226, 2020). "STAT3 may be activated by cytokines such as IL-6 and IL-10 that, released by tumor cells, besides acting in an autocrine fashion to sustain cancer cell survival, may activate this pathway in myeloid immune cells in the tumor environment, resulting in an impairment of their function." (PMID 32754441, 2020). "Therefore, Treg may not exert an important effect in CD8+ cell recruitment and function, but another population such as TAMs, through IL-10 secretion or tumor cell direct contact, could promote CD8+ cell impairment." (PMID 32547942, 2020). "Also, the levels of IL-1β and IL-6 decreased, but the level of IL-10 increased, which may reduce the cytokine-induced tumor immunosuppressive activity, cancer progression and cancer cachexia syndrome." (PMID 33013406, 2020). "Signal Transducer and Activator of Transcription 3 (STAT3) mediates the intracellular signaling of tumor-associated immunosuppressive cytokines, such as interleukin (IL)-10; thus, we hypothesized that STAT3 restrained anti-tumor immune responses elicited by CD103+ cDC1s." (PMID 31947933, 2020). "Furthermore, IL-10 and IL-35 augmented their cooperation to limit antitumor immunity by inducing inhibitory receptors, including PD-1, and contributing to T-cell exhaustion of CD8+-Tregs once the tumor cells recurred, because IL-10 was abundantly secreted by tumor cells in B-cell VRL." (PMID 32973297, 2020). "Furthermore, immature dendritic cells (iDC) responded to mCD40L with enhanced maturation and activation over sCD40L evidenced by higher expression levels of CD83, CD86, HLA-DR and CD54, increased secretion of IL12 and IL10 and higher tumour-antigen (TA) uptake capacity." (PMID 31941968, 2020). "In details, in all the analyzed patients and independently from the tumor site of origin, the levels of IL-6 increased after 10 days of treatment with lanreotide and decreased in the following six months; whereas the levels of IL-2 and IL-10 raised only in some patients." (PMID 32766136, 2020). "Moreover, tumor cells may also produce immunosuppressive cytokines, namely interleukin (IL)-10 and transforming growth factor (TGF) beta that inhibit the function of NK cells." (PMID 32414037, 2020).
tumor (continued). "Tumor-associated cells residing at the tumor site, including immature dendritic cells (DCs), Tregs, tumor-associated macrophages, and myeloid-derived suppressor cells, produce various molecules such as TGF-β, IL-4, IL-10, prostaglandin E2, and idoleamine 2,3-dioxygenase." (PMID 32391048, 2020). "Thus, tumor cells can induce M2-type differentiation of macrophages by secreting IL-4 and IL-10." (PMID 33224886, 2020). "Finally, TGF-β, IL-10, and other inhibitory cytokines secreted by the tumor microenvironment may limit the effect of gp96 tumor vaccines, similar to the limits of other immunotherapies." (PMID 32922959, 2020). "Noteworthy, other biological events may also contribute to IL-10 mediated tumor progression." (PMID 32850405, 2020). "Additionally, the increased levels of IL-10 in miliary samples may account for an inhibition of NETosis, thus supporting miliary kind of tumor spread." (PMID 32098278, 2020). "While CCL3 and IL10 (upregulated in FI-like tumors) have been described as molecules able to elicit antitumor response, the molecules upregulated in OSE-like tumors have all been associated with the induction of immunosuppressive response and increased tumor invasiveness." (PMID 33121525, 2020). "In addition to regulating myeloid-origin cells such as MDSC and tumor-associated macrophages (TAM), C5aR1 and the complement anaphylatoxin C3a receptor (C3aR) synergistically impair cytolytic activity of tumor infiltrating CD8+T cells (TIL) by inhibiting expression of IL-10 in these cells." (PMID 33488603, 2020). "Indeed, multiple mechanisms are at play in the tumor to prevent tumor cell killing by immune cells, via myeloid-derived suppressive cells, regulatory T cells or the secretion of immunosuppressive factors (e.g., IL-10, TGFβ, IDO)." (PMID 32117911, 2020). "Furthermore, tumour cells may interfere with DC maturation through the secretion of IL-10, which results in the induction of antigen-specific energy." (PMID 32565898, 2020). "Correspondingly, IL-10 and TGF-β can drive the differentiation of monocytes into M2-like tumor-associated macrophages (TAMs), which amongst their other suppressive actions, can also compete with local dendritic cells (DCs) for tumor antigens and consequently inhibit T cell priming." (PMID 32290124, 2020). "The tumor growth and vascular density seemed to be independent from inflammatory infiltrate of tumors, but in ex vivo stimulated immune cells, these correlated with reduced cytokine production including IL-12 and IL-10 produced in macrophages, IL-10 in B cells, and IFN-γ in T cells." (PMID 33271774, 2020). "In addition, the systemic elevation of some cytokines, such as TNFα, IL-6, IL-8, and IL-10, observed in GD patients, which are known to promote tumor development, could be involved in the increased tumor growth we observed." (PMID 32085512, 2020). "Therefore, the correlation between the percentage of CD4+CD25+CD127lowTregs and the concentrations of TGF-β1 and IL-10 in this study will provide some insight for more in-depth studies on the tumorigenetic mechanism, and facilitate the development of more effective tumor treatment programs." (PMID 32218692, 2020). "Therefore, from our retrospective clinical studies, IL-10 may play a role as pro-tumor effects in vivo." (PMID 33154947, 2020). "Interestingly, this study has shown that blocking the PD-1 by neutralizing antibodies was associated with increased IL-10 production by DCs and this did not result in a change in the immunosuppressive microenvironment of the tumour, indicating that IL-10 compensates for the PD-1 blockade." (PMID 32931721, 2020). "In supernatants derived from RANK+/+ tumor acini, many cytokines were upregulated including stromal cell-derived factor-1α, macrophage inflammatory protein-1α, interleukin (IL)-1α, stem cell factor, tumor necrosis factor-α, IL-13, macrophage colony-stimulating factor, IL-10, IL-4, IL-17, and IL-1β." (PMID 33303745, 2020).
tumor (continued). "However, in some types of cancer, IL-10 can perform both anti-tumor and pro-tumor activities." (PMID 33126617, 2020). "However, in another study, a murine tumour model treated with genetically modified lactic acid bacteria (GM-LAB) and engineered to produce IL-10 or antioxidant enzymes showed CC tumour inhibition 125, indicating that IL-10 might suppress tumour growth." (PMID 32760201, 2020). "Given the newfound appreciation of the complexity of the TIL-B sub-populations, a more effective approach may involve depleting specific pro-tumor subsets, such as Bregs and IL-10+ B cells, while promoting anti-tumor subsets which could be combined with CPI as an adjuvant." (PMID 33569063, 2020). "Importantly, even though tumor cells initially trigger the expression of suppressive cytokines (such as interleukin-10, IL-10), stromal cells are often the main producers of these suppressive factors, which in turn will result in the immune suppressive microenvironment found in cancer patients." (PMID 32507967, 2020). "Thus, tumor associated macrophages (TAM) and other immature myeloid cells (myeloid derived suppressor cells, MDSC) can polarize a Th2 response and/or produce suppressive factors such as IL-10, TGF-β, ROS or deplete intracellular L-arginine." (PMID 32218226, 2020). "Furthermore, as cytokines can assist tumor progression, targeting IL-4, IL-13, IL-10, TGF-β, and CXCL5 or enhancing IFN-γ and some chemokines (e.g., CCL2, CCL3, CXCL9, CXCL10) may inhibit tumor invasion and metastasis." (PMID 32346605, 2020). "Notably, M2-activated macrophages, which are considered to be the majority of Tumor-associated macrophages (TAMs) within a tumor, release significant amounts of IL-10, which could indicate a correlative relationship between IL-10 and tumor progression." (PMID 33614473, 2020). "The ICOS-driven interaction between tumor associated CD4+ T cells and ICOSL-expressing TA-pDCs sustain the expansion of ICOS+ FoxP3+ Tregs in the tumor microenvironment and promote the secretion of IL-10 and TGF-β from Tregs, which support an immunosuppressive microenvironment and tumor progression." (PMID 32054102, 2020). "In addition to inflammatory factors such as IL-10 and GM-CSF, other factors such as tumor cell-released autophagosomes (TRAPs), long non-coding RNA HOXA transcript at the distal tip (HOTTIP), and IL-6 from cancer-associated fibroblasts (CAFs) have also been reported to regulate PD-L1 expression." (PMID 32477934, 2020). "The analysis of IL-10 levels showed that the mice groups treated with fish oil (p < 0.05) or soybean oil (p < 0.05) or the mixture of these oils (1:1 ratio, p < 0.01) showed increased levels of this anti-inflammatory cytokine in the tumor homogenate compared to control group." (PMID 31374840, 2019). "Moreover, blocking immunosuppressive molecules (TGF-β, IL-10) expressed either by cancer cells or by tumor-infiltrating immune cells could represent another therapeutic strategy for the treatment of TC." (PMID 31412566, 2019). "Moreover, tumor cells can escape immune surveillance cells, promoting immune tolerance to the tumor by favoring the establishment of a Th2 immune response, expressing cytokines like IL-4, IL-10, and TGF-β." (PMID 31861795, 2019). "Therefore, transient expression of IL-10 trap through NP intratumoral delivery could change cytokines and tumor-infiltrating lymphocytes within the TME, resulting in significant antitumor efficacy." (PMID 30871158, 2019). "Moreover, IL-10 was reduced in the tumour and butyrate groups." (PMID 30626010, 2019). "Under the influence of tumor-derived factors, TAMs could also secrete an array of cytokines, including IL-10, transforming growth factor-β (TGF-β) and prostaglandin-E2 (PGE2), that further inhibit T cell-mediated immune response to establish a self-propagating immunosuppressive TME." (PMID 31805946, 2019).
tumor (continued). "IL-10 is an important anti-inflammatory cytokine and due to its immunosuppressive effect on dendritic cells and macrophages, IL-10 can dampen antigen presentation, cell maturation and differentiation, allowing tumor cells to evade immune surveillance mechanisms." (PMID 31086100, 2019). "Considering recent reports, we speculate that the synthesis of NO and IL-10 by tumor-infiltrating macrophages and Tregs would constitute the ground to the inhibition of a protective Th1 response and the condition to the development of IL-10-associated LSCC's loco-regional metastases risk." (PMID 31885577, 2019). "Taken together, these results suggest that IL-10 –819TT and -592AA genotypes are associated with a decreased risk for GC by maintaining a low expression of IL-10, which could then favor the APC’s access to the tumor cells and the infiltration of CD8 + T lymphocytes." (PMID 31092242, 2019). "We previously showed that temporal locking of IL-10 signalling at the time of immunisation drastically increases vaccine induced cytotoxic T cell responses compared with the same vaccine without IL-10 signalling blockade, and reduced tumour growth in an animal tumour model." (PMID 30897137, 2019). "However, the inflammation that potentially takes part in the DC maturation may, conversely, facilitate the tumor progression through signals driven by IL-10 and TGF-β which are also major effectors of regulatory T-cells (Treg) development." (PMID 31750245, 2019). "In addition, the tumour expression of IL-10, TNF-α and TGF-β was analysed by RT-PCR." (PMID 31731436, 2019). "Moreover, we observed a decrease in the frequency and total number of M1-like and M2-like macrophages within the myeloid compartment, the latter being a key source of intratumoral IL10, indicating that poly A:U reduces the amount of this immunosuppressive cytokine present in the tumor." (PMID 30949170, 2019). "Taken together, these data suggest that MOv18 IgE may support TAM populations with mature phenotypes and hybrid M1/M2 features that are able to enter the tumour, trigger sustained immune activating pathways and secretion of IL-10, TNFα, MCP-1 and IL-1α in tumour-bearing lungs." (PMID 31544825, 2019). "Activating mutations in oncogenic RAS/BRAF/MEK pathways trigger a tumor-intrinsic inflammatory network with the concerted regulation of master transcription factors (TFs) including STAT3, NF-κB and AP-1 which in turn trigger the expression of cytokines, including IL-6, IL-1, IL-10, TNF and VEGF." (PMID 31766350, 2019). "IL-10 is produced by various types of immune cells, including T regulatory cells (Tregs), T helper cells (Th)-1, Th17, B cells, activated monocytes, macrophages, mast cells, granulocytes, dendritic cells (DC) and tumor cells, thus preventing the inflammatory environment created by cancer." (PMID 32039024, 2019). "In addition, chemotherapeutics modifies the levels of several cytokines, down-regulates immune suppressive cytokines (i.e., transforming growth factor-β (TGF β) and IL10), and up-regulates cytokines promoting tumor immunity (i.e., tumor necrosis factor-α (TNF-α), IL-2, and interferon (IFN)–γ)." (PMID 30991686, 2019). "Although pDCs may promote tumour development through indoleamine 2,3‐dioxygenase expression 21 and induction of regulatory T‐cell expansion 22, a few studies have reported that pDCs can secrete IL‐10 in response to environmental stimuli." (PMID 31418859, 2019). "Moreover, i.v. vaccination with the liposome-containing tumour antigens and IL-10 siRNA induced type- I- interferon production and cytotoxic T cell responses against tumour cells, further supporting the use of lipid based nano-carrier agents for the activation of DCs in situ as well." (PMID 30717461, 2019).
tumor (continued). "At advanced stages of cancers, including lung cancer, the tumor tissues become highly immunosuppressive due to the infiltration by immunoinhibitory cells such as Tregs and MDSCs and/or the generation of inhibitory factors such as PD-1/PD-L1, lymphocyte activation gene-3, IL-10, and TGFβ." (PMID 30972427, 2019). "Th2 cytokines such as IL-6 and IL-10 enhance motility and survival of highly tumorigenic cancer stem cells and thus metastasis, while IL-8 is involved in the regulation of angiogenesis, cancer cell growth and survival, tumor cell motion, leukocyte infiltration, and modification of immune responses." (PMID 31448052, 2019). "Immune suppressive cytokines such as IL10, TGFβ and VEGF, regulatory T cells, and macrophages with a deviated maturation (myeloid-derived suppressor cells) are abundantly present in the tumor microenvironment, causing even aggressive activated anti-tumor cytotoxic T cells to become inactive." (PMID 31628559, 2019). "Therefore, CD19+ Tim‐1+ cells with IL‐10 production could be also induced in young KO mice transplanted with tumour cells." (PMID 30467955, 2019). "Based on our observation of a consistent increase in local and systemic IL-10 concentrations, associated with elevated numbers of CD4+ T cells in the lungs of metformin-treated tumor-bearing mice, we subsequently assessed whether Treg cells could be induced in this context." (PMID 29899823, 2018). "However, whether IL-10 secreted by ALK-positive tumor cells affects MHC class II expression in ALCL patients has not been shown directly." (PMID 29642597, 2018). "Although the elevated level of IL-10 over IL-12 suggests the predomination of Th2 response during the treatment, further studies are necessary to exactly determine the type of cells that adopts such a behavior in response to treatment with calcitriol and its analogs during tumor progression." (PMID 30037009, 2018). "A recent study has suggested that IL-10 could be involved in the immune evasion of tumour cells." (PMID 30539028, 2018). "In addition, STAT3 signaling has been found to regulate both innate and adaptive immunity by increasing the expressions of growth factors and cytokines including TGF-β, VEGF, interleukin 6 (IL-6), and IL-10, which collectively repress the host immune response and facilitate tumor immune evasion." (PMID 30046565, 2018). "However, IL-10 and IL-4 are also responsible for pro-tumor cell polarization." (PMID 35847834, 2018). "These positive feedback loops are generated by cytokines such as TGF-β, Interleukin-10 and Interleukin-4, which are responsible for the polarization of monocytes and M1 macrophages into pro-tumor M2 macrophages, and the polarization of naive helper T cells intopro-tumor Th2 cells." (PMID 35847834, 2018). "Interestingly, CD200fc differentially altered IL-10 response to LPS and irradiated tumor challenge." (PMID 29721190, 2018). "B cell production of IL-10 may aid in antitumor immunosuppression by T cell inhibition, whereas competition with tumor cells (H-RS) for T-cell derived survival signals may halt tumor cell growth." (PMID 30101129, 2018). "Because the age-dependent high levels of IL-10, IL-4 and IL-5 were subsequently decreased by tumor induction only in multiparous mice in the present model, we suggest that parity during fertile life might improve antitumor immunity in aged mouse challenged with tumor-inducing cells." (PMID 28966800, 2017). "However, PDL-1 is expressed in tumor cells and antigen presenting cells (APCs), and the engagement of PD-L1 with PD-1 of T cell creates T cell dysfunction, exhaustion, neutralization, and interleukin-10 (IL-10) production in a tumor mass." (PMID 28878676, 2017). "Within the tumor microenvironment, monocytes are induced to differentiate and polarize into protumoral macrophages through complex signaling networks induced by multiple soluble mediators, such as M-CSF, GM-CSF, and immunosuppressive cytokines such as IL-4, IL-10, and TGF-β." (PMID 28955335, 2017).